POMC (proopiomelanocortin)
Diseases named in the same sentence as POMC in open-access papers (continued):
Sharing a sentence is not in itself a finding about the gene and the disease.
cognitive decline (4 papers, 2018 to 2025). "POMC signaling in these regions has been implicated in the cognitive decline of Alzheimer’s disease." (PMID 32483278, 2020). "Taken together, those changes in mRNA expression as well as POMC and NPY-expressing neuronal alterations suggest that exercise training is sufficient to change outcomes related to hypothalamic function in the 3xtg-AD model at a critical point before the development of cognitive decline." (PMID 29293568, 2018).
leukemia (4 papers, 2015 to 2024). A malignant (clonal) hematologic disorder, involving hematopoietic stem cells and characterized by the presence of primitive or atypical myeloid or lymphoid cells in the bone marrow and the blood.
obesity syndrome (4 papers, 2021 to 2025). "In contrast to some monogenic obesity syndromes, which display classical Mendelian inheritance (LEP, LEPR, POMC and PCSK1), rare heterozygous variants in HTR2C are generally not fully penetrant." (PMID 36536256, 2022).
parathyroid adenomas (4 papers, 2017 to 2025). "provided direct evidence for promoter hypermethylation of the pro-opiomelanocortin (POMC) gene in parathyroid adenomas." (PMID 41210508, 2025). "In our study, compared to normal parathyroid tissue, parathyroid adenoma showed hypermethylation of the CpG island in POMC." (PMID 35974370, 2022). "The expression of POMC protein was analyzed in normal parathyroid and parathyroid adenoma FFPE samples via immunohistochemistry." (PMID 35974370, 2022). "Compared to normal parathyroid adenomas, the expression of POMC protein in parathyroid adenomas was significantly decreased." (PMID 35974370, 2022). "Low expression and hypermethylation of POMC in parathyroid adenoma." (PMID 35974370, 2022). "In addition, POMC protein in parathyroid adenomas was mainly expressed in the cytoplasm, while in normal parathyroid samples, it was also expressed in the nucleus." (PMID 35974370, 2022). "The mRNA expression of POMC in parathyroid adenoma was validated via qRT-PCR." (PMID 35974370, 2022). "However, the expression of POMC in parathyroid adenomas was markedly lower than that in normal parathyroid tissue." (PMID 35974370, 2022).
POMC deficiency (4 papers, 2018 to 2024). "Congenital POMC deficiency develops due to genetic defects in the POMC gene located at Chr.2p23.3." (PMID 28739551, 2018).
prediabetes (4 papers, 2022 to 2024). "The following sections will discuss how the risk factors associated with prediabetes are also associated with MI and how they influence POMC derivatives." (PMID 38397916, 2024). "The effect of prediabetes on POMC derivatives has yet to be fully explored and understood." (PMID 38397916, 2024). "This study sought to review the potential impact of prediabetes on the POMC derivatives and pathways that could lead to MI." (PMID 38397916, 2024). "The review aims to discuss the potential impact of prediabetes on POMC derivatives and pathways that could lead to MI." (PMID 38397916, 2024).
Alström syndrome (3 papers, 2022 to 2023). "These consequences are related to proopiomelanocortin (POMC), proprotein convertase subtilisin/kexin type 1 (PCSK1), or leptin receptor deficiency (LEPR), as well as other rare genetic diseases, including BBS and Alström syndrome." (PMID 37888071, 2023).
celiac disease (3 papers, 2020 to 2025). An autoimmune genetic disorder with an unknown pattern of inheritance that primarily affects the digestive tract. "α-MSH is a peptide derived from the hormone proopiomelanocortin (POMC), which is capable of reducing inflammation in endotoxin-induced uveitis and in duodenal mucosa in celiac disease patients." (PMID 32751786, 2020).
colorectal cancer (3 papers, 2013 to 2022). A primary or metastatic malignant neoplasm that affects the colon or rectum. "Genes coexpressed with CDH4 were correlated with “Protein folding and maturation POMC processing”, “Beta-catenin-dependent transcription regulation in colorectal cancer”, and “Cell adhesion_ECM remodeling”." (PMID 36315446, 2022).
cystic fibrosis (3 papers, 2022 to 2023). Autosomal recessive disorder caused by pathogenic variants in the CFTR gene (cystic fibrosis transmembrane conductance regulator), which encodes a chloride and bicarbonate channel expressed in epithelial cells, and follow the diagnosis criteria. "Our recent study in cystic fibrosis patients showed reduced POMC levels compared to controls." (PMID 36986097, 2023). "Due to the longer life of the patients and the emerging diseases accompanying cystic fibrosis, it seems necessary to organize further studies to fully explore the physiology of KISS and POMC in CF." (PMID 36271282, 2022).
melasma (3 papers, 2020 to 2025).
non-small cell lung carcinoma (3 papers, 2023 to 2025). A group of at least three distinct histological types of lung cancer, including non-small cell squamous cell carcinoma, adenocarcinoma, and large cell carcinoma. "Indeed, POMC is expressed in tumor tissues in 48% of patients with non-small cell lung cancer, with only a few cases manifesting as EAS with excess cortisol." (PMID 38035072, 2023).
pancreatic insufficiency (3 papers, 2025 to 2026). "This indicates that the blunted response of insulin in POMC-Cre ERt2:: FASNflox/flox mice is not due to pancreatic insufficiency, but rather to increased sympathetic tone." (PMID 40541585, 2025).
Coronary Artery Disease (2 papers, 2013 to 2018). "To further investigate the association between POMC and reverse cholesterol transporters, we analyzed whole blood and circulating monocyte samples from patients with coronary artery disease (CAD) and compared them with angiographically normal controls (non-CAD)." (PMID 30305673, 2018). "First, transcript levels of POMC and its processing enzymes were analyzed in human arterial plaques (n = 68) and non-atherosclerotic controls (n = 24) as well as in whole blood samples from coronary artery disease patients (n = 55) and controls (n = 45) by microarray." (PMID 30305673, 2018).
degenerative joint diseases (2 papers, 2014 to 2018). "Understanding the underlying molecular mechanisms of the functional role of the POMC system in joints will eventually help to tailor efficient future therapies against degenerative joint diseases as OA." (PMID 25191747, 2014).
diabetic neuropathy (2 papers, 2021). A chronic, pathological complication associated with diabetes mellitus, where nerve damages are incurred due to diabetic microvascular injury involving small blood vessels that supply these nerves, resulting in peripheral and/or autonomic nerve dysfunction. "Overexpression of POMC-derived endo-opioids in L3–L4 DRG does not change baseline nociception in female mice but suppresses diabetic neuropathy-induced hypersensitivity." (PMID 34497285, 2021). "Moreover, reduction of already low levels of POMC expression in DRG neurons of female and male mice with diabetic neuropathy contributes to hypersensitivity." (PMID 34497285, 2021).
influenza (2 papers, 2022 to 2023). An acute viral infection of the respiratory tract, occurring in isolated cases, in epidemics, or in pandemics; it is caused by serologically different strains of viruses (influenzaviruses) designated A, B, and C, has a 3-day incubation period, and usually lasts for 3 to 10 days. "While most neuronal subpopulations follow this same regulatory pattern, POMC+ neurons show bigger and more unique changes in gene regulation following a peripheral influenza infection." (PMID 37698546, 2023).
amyloid (1 paper, 2021). "Accordingly, we overexpressed POMC protein in POMC neurons in the CA3 region in APP/PS1 mice at 8 months of age, when amyloid plaque deposition is extensive in the brain." (PMID 33623128, 2021).
autism spectrum disorder (1 paper, 2021). A spectrum of developmental disorders that includes autism, and Asperger syndrome. "Among other transcript isoforms dysregulated by MIA in the amygdala, the detection of POMC is in agreement with our analysis at the gene level and with reports of pre- and post-translational bioactive forms associated with behaviors observed in autism spectrum disorders." (PMID 33834688, 2021).
embryonal carcinoma (1 paper, 2025). A non-seminomatous malignant germ cell tumor characterized by the presence of large germ cells with abundant cytoplasm resembling epithelial cells, geographic necrosis, high mitotic activity, and pseudoglandular and pseudopapillary structures formation. "Expression of genes involved in general steroid biosynthesis (STAR, POMC, CYP11A1, FDX1) and the aromatase-coding gene CYP19A1 was the highest in embryonal carcinomas." (PMID 40011822, 2025).
endometrial cancer (1 paper, 2023). Primary or metastatic malignant neoplasm involving the endometrium (mucous membrane that lines the endometrial cavity). "Endometrial cancers that express ACTH or POMC are very rare, and immunohistochemistry revealed no ACTH expression in endometrial cancer tissues in our cases (data not shown)." (PMID 40729185, 2023).
glucose metabolic disorders (1 paper, 2018). "Peripheral insulin administration efficiently attenuated liver dysfunction and glucose metabolic disorders by suppressing hypothalamic anorexigenic neuropeptide proopiomelanocortin (POMC) expression, hepatic NF‐κB pathway and STAT3 phosphorylation." (PMID 29285858, 2018).
Inguinal hernia (1 paper, 2024). Protrusion of the contents of the abdominal cavity through the inguinal canal. "The IVW method indicates that genetically-predicted POMC (OR [95%]=0.716 [0.5287 to 0.9717], p = 0.0319) and VWF (OR [95%]=0.9988 [0.9976 to 0.9999], p = 0.0363) possess a clear protective effect on unilateral inguinal hernia." (PMID 38591204, 2024).
lung fibrosis (1 paper, 2017). "αMSH as a tridecapeptide derived from POMC displays potent anti-inflammatory role in many tissues and has protective effects on therapies in brain damage, liver or lung fibrosis, skin inflammation and chronic adipose inflammation." (PMID 28514752, 2017).
morphine dependence (1 paper, 2013). Strong dependence, both physiological and emotional, upon morphine. "Morphine dependence and two hours’ opiate withdrawal affected AVP and POMC mRNA levels in the hypothalamus." (PMID 23805290, 2013).
neuropathic pain (1 paper, 2009). Chronic pain caused by damage to nerve fibers. "For example, intrathecal electroporation of modified POMC plasmids suppressed thermal hyperalgesia in a neuropathic pain model, and PPENK-HSV applied to the paw skin reversed thermal hyperalgesia induced by pertussis toxin or capsaicin." (PMID 20003437, 2009).
panic disorder (1 paper, 2024). An anxiety disorder characterized by multiple unexpected panic attacks with persistent concern of recurring attacks. "The purpose of this study was to investigate the effects of escitalopram on the peripheral expression of hypothalamic-pituitary-adrenal (HPA) axis-related genes (FKBP51, HSP90, NR3C1 and POMC) and HPA-axis hormones in patients with panic disorder (PD)." (PMID 38600448, 2024).
substance abuse (1 paper, 2021). The use of a drug for a reason other than which it was intended or in a manner or in quantities other than directed. "Some of us previously investigated involvement of eight genes in the opioid system (OPRD1, OPRK1, OPRL1, OPRM1, PDYN, PENK, PNOC, and POMC) and their potential effects on substance abuse." (PMID 34440333, 2021).
temporal lobe epilepsy (1 paper, 2019). A localization-related (focal) form of epilepsy characterized by recurrent seizures that arise from foci within the temporal lobe, most commonly from its mesial aspect. "We used the intrahippocampal kainate injection model of temporal lobe epilepsy to study post-kainate neurogenesis in the hippocampus of adult male POMC-EGFP mice." (PMID 31596871, 2019).
tumor (600 papers, 1989 to 2026). "We now describe a novel missense USP8 variant c.1724 C > A in the left tumor of our patient which when overexpressed, resulted in increased POMC transcription, but weaker than that observed with the hotspot USP8 mutation S718P." (PMID 40544420, 2025). "Functional studies in murine corticotroph tumor cells demonstrated that GPR162 negatively regulates POMC mRNA expression and the GPR162 variant R218* that we had demonstrated in our index patient blunted the suppressive effect of WT GPR162." (PMID 40544420, 2025). "The novel USP8 variant (P681Q) found in the contra-lateral tumor led to increased POMC transcription although weaker than the well characterized hotspot variant S718P, and did not affect EGFR ubiquitin." (PMID 40544420, 2025). "Roscovitine has dual effects; inhibition of corticotroph tumor growth and suppression of transcription of POMC, which encodes a precursor of ACTH." (PMID 33841328, 2021). "The involvement of the hormones associated with corticotropin-releasing hormone (CRH)-proopiomelanocortin (POMC) axis in the tumor development process has also prompted the interest of researchers." (PMID 29854027, 2018). "Although it is true that a rise in POMC would indicate relapse following radiotherapy, the tumour burden with which this is associated would be much greater than that observed without radiation treatment." (PMID 26848743, 2016). "and Dysregulation of GAST has also been associated with the development of various types of cancers,Additionally, POMC expression may be associated with tumor malignancy." (PMID 40098956, 2025). "Clinically, while BRAF-mutated tumors have been associated with increased POMC transcription and ACTH secretion, there is currently limited data on their phenotype, including tumor size, invasiveness, or treatment response, due to the rarity of these mutations." (PMID 40364036, 2025). "Interestingly, this patient’s complicated with a tumor that ectopically expressed POMC, suggesting that the IAD was caused by a form of paraneoplastic syndrome in the case." (PMID 33977343, 2021). "Paraneoplastic−like processes—where tumor-derived ectopic POMC expression triggers auto−reactivity to corticotrophs—have been described, particularly in patients treated with anti–PD−1/PD−L1 agents." (PMID 41189622, 2025). "Ectopic expression of proopiomelanocortin (POMC) has been identified on tumor cells of various primary malignancies." (PMID 41002414, 2025). "To further determine the effects of USP8 variants on the POMC promoter activity, we transfected the POMC luciferase reporter in combination with plasmids expressing USP8-WT and the USP8 variants into murine corticotroph tumor cells." (PMID 40544420, 2025). "In this study, the POMC gene was markedly overexpressed across all ACTH-secreting tumor samples, exhibiting the highest expression in pituitary ACTH-secreting tumors, where it was elevated ~30-fold relative to normal pituitary tissue." (PMID 40002253, 2025). "The knockdown of USP11 in both in vitro cell lines and in vivo mouse models leads to reduced POMC expression and ACTH levels, confirming its functional role in tumor behavior." (PMID 40364036, 2025). "As a result, TR4 overexpression attenuated GR-mediated inhibition of POMC transcription in AtT-20 cells and human corticotroph tumor cells." (PMID 36672445, 2023). "Meanwhile, we found that tumor transplantation resulted in the activation of neurons in the paraventricular nucleus of the hypothalamus and increased POMC expression in the intermediate lobe of the pituitary gland." (PMID 39872954, 2023).